TRH (thyrotropin releasing hormone)
Diseases named in the same sentence as TRH in open-access papers (continued):
Sharing a sentence is not in itself a finding about the gene and the disease.
Tremor (1 paper, 2024). An unintentional, oscillating to-and-fro muscle movement about a joint axis. "Nevertheless, only one study has been conducted which demonstrated that TRH triggered myoclonus and tremor similar to the symptoms that patients experience during exacerbation of HE symptoms." (PMID 39000209, 2024).
viral infection (1 paper, 2024). "Our findings have revealed new insights into the regulation of TRH cells in respiratory traction after viral infection." (PMID 38345472, 2024). "We further delved into the cellular mechanisms that uphold TRH cells within the TLS after viral infections and found that B cell MHCII was required for the optimal maintenance of TRH cells." (PMID 38345472, 2024).
Whipple disease (1 paper, 2006). A systemic infection caused by the Gram-positive bacterium Tropheryma whipplei. "Thyrotropin releasing hormone testing in the steady state suggested there was diminished thyroid reserve due to Whipple's disease." (PMID 16684360, 2006).
Zinc deficiency (1 paper, 2024). A deficiency of the essential metal Zinc; an essential cofactor for many enzymes. "Zinc deficiency can affect the synthesis of thyrotropin releasing hormone (TRH), and the levels of thyrotropin (TSH), T3 and T4 will decrease." (PMID 38386169, 2024).
cancer (16 papers, 2010 to 2025). A tumor composed of atypical neoplastic, often pleomorphic cells that invade other tissues. "Beyond its endocrine functions, TRH has been linked to cancer development and progression." (PMID 41465216, 2025). "Studies have shown that TRH can treat the symptoms of significant fatigue in cancer patients and enhance the body’s immunity." (PMID 40017690, 2025). "We found that the expression level of TRH was actually low in most cancers and matched normal tissues." (PMID 36291567, 2022). "In this work, we investigated the distribution of TRH expression in cancers, especially in different subtypes of AML." (PMID 36291567, 2022). "During angiogenesis in cancer cells, NUPR1 was reported to be upregulated in association with triiodothyronine thyroid hormone receptor, which is regulated with TRH - Thyrotropin releasing hormone." (PMID 33008348, 2020). "Using real-time PCR, TRH methylation was detected in cancer epithelial cells collected using both oral rinse and oral swab." (PMID 30081853, 2018). "It would be interesting to detect TRH gene methylation in other HPV-related cancers." (PMID 41465216, 2025). "TRH was utilized to treat cancer-related fatigue in patients and showed considerable improvement." (PMID 37766209, 2023). "In fact, through the query of the RNA-seq data of pan cancer, TRH was barely expressed in a variety of cancers, which might be attributed to its methylation status." (PMID 36291567, 2022). "Thus, the expression and clinical analysis in pan-cancers showed that TRH was a unique biomarker for AML." (PMID 36291567, 2022). "Although the function of TRH in cancer is currently unknown, methylation of the TRH gene in cancerous cells revealed in this study and previous studies suggest that TRH functions involving carcinogenesis as a tumor suppressor gene." (PMID 30081853, 2018). "MESOR of cortisol, TRH, GH, IL-2 and CD16 was increased, whereas MESOR of TSH, IGF-1, CD8, CD8bright, TcRδ1 and δTcS1 was decreased in cancer patients." (PMID 20565977, 2010). "MESOR of cortisol, TRH, GH, IL-2 and CD16 was increased in cancer patients, whereas MESOR of TSH, IGF-1, CD8, CD8bright, TcRδ1 and δTcS1 was decreased in cancer patients." (PMID 20565977, 2010). "GNB3, TRH, and TYMS also play important roles in human cancers." (PMID 35494074, 2022).
tumor (14 papers, 2011 to 2024). "In our case, diffuse co-secretion of both TSH and TRH was seen in the tumor cells, which is an undisputed cause of SITSH." (PMID 32706866, 2020). "The temperature measured by the TRH Central probe within the tumor rapidly reached to ∼53°C within 2 to 3 min of NIR laser exposure on the skin surface above the tumor in GNR-PEG-injected mice and GNR/anti-CA IX-injected mice." (PMID 29899876, 2018). "While 96% of TSH-secreting tumor presented a blunted TSH response to the TRH test and 97% of RTH were excited by TRH." (PMID 25069990, 2014). "The aim of this study was to investigate how the paradoxical response of GH secretion to TRH changes according to tumor volume in acromegalic patients." (PMID 24348552, 2013). "Others proposed that TRH directly activates the tumor cells, or that LH-RH stimulation increases metabolic activity leading to vascular accidents." (PMID 22934202, 2012). "The increase in PRL secretion quantity due to inhibition of the action of prolactin inhibiting factor by tumor compression to the hypothalamus might suppress TRH-stimulated PRL response." (PMID 37484278, 2023). "It would be interesting to know whether TRH administration would result in an increase in plasma ACTH concentration in dogs with PDH due to a PI tumor." (PMID 30362899, 2018). "This tumor is made of cells responding most frequently to TRH (>70%) but all cells store GH (100%)." (PMID 26106585, 2015). "Leptin may promote tumor growth by signaling through normal endocrine pathways: Physiologic binding of leptin to its receptors on hypothalamic neurons leads to Thyrotropin-releasing hormone (TRH) production by these cells." (PMID 36973672, 2023). "Therefore, the presence of this mutation may not be sufficient to explain the relationship between responsiveness of GH to TRH and tumor volume." (PMID 24348552, 2013). "Thus, unlike the previous findings, it can be further hypothesized that these two mechanisms may behave synergistically to result in the increase of GH secretion after TRH administration as the tumor volume increases." (PMID 24348552, 2013). "The tumor was positive for thyrotropin (TSH), TSH-releasing hormone (TRH), Pit-1, GATA-2, and most neuronal markers." (PMID 32706866, 2020). "When only patients with macroadenomas were analyzed, ΔGHmax-min during the TST were significantly higher in TRH responders (105.8 ± 138.1 versus 34.8 ± 30.1 μg/L, P = 0.024: P value not shown in the table), while tumor volumes were not significantly different." (PMID 24348552, 2013). "Immunohistochemical studies revealed diffuse co-secretion of both TRH and TSH by the tumor, with diffuse expression of lineage-restricted transcription factors (ie, Pit-1 and GATA-2), which may have resulted in a continuous autocrine/paracrine regulation of TSH secretion." (PMID 32706866, 2020). "The difference in TRH-induced ACTH secretion in horses with PPID and the dogs in this study with PDH may be explained by the fact that none of the PDH dogs included in this study obviously had a PI tumor." (PMID 30362899, 2018). "In fact, <10% of cells from these tumors responded to CRH, LHRH, TRH, and GHRH, with little or no intra-tumor differences." (PMID 26106585, 2015). "Between TRH responders and nonresponders, basal GH, IGF-I levels, peak GH levels, and tumor volume were not significantly different, but the between-group difference of GH levels remained near significant over the entire TST time." (PMID 24348552, 2013). "Between TRH responders and nonresponders, basal GH, IGF-I levels, and tumor volume were not significantly different but the between-group difference of GH levels remained near significant over the entire TST time." (PMID 24348552, 2013).
neurodegenerative disease (7 papers, 2011 to 2023). A disorder of the central nervous system characterized by gradual and progressive loss of neural tissue and neurologic function. "We found TRH- or TAL-induced changes in some signaling pathways associated with neurodegenerative disease pathology." (PMID 35563779, 2022). "Some of the functions of TRH in the context of pathological aging and neurodegeneration, and the potential of TRH and TRH mimetics for the treatment of neurodegenerative diseases have been discussed elsewhere." (PMID 36147745, 2022). "The close association of TRH-R-mediated effects with dopaminergic and cholinergic signaling appears to be crucial in the potential use of TRH and its analogs for the treatment of neurodegenerative diseases." (PMID 36147745, 2022). "While MS is an immune neuroinflammatory condition and ALS is a neurodegenerative disease, both share some symptoms, and may benefit from TRH’s neuroprotective actions." (PMID 37446225, 2023). "While thyrotropin-releasing hormone is known to be a prolactin-release stimulating factor, thyrotropin-releasing hormone-tartrate and its derivative, taltirelin hydrate, are used for the treatment of spinocerebellar degeneration, a degenerative disease characterized mainly by motor ataxia." (PMID 22152284, 2011). "The discovery of this novel TRH receptor subtype (which is pharmacologically different from the one already described) will help to draw attention to the use of TRH analogs to treat the symptoms of ALS and other neurodegenerative diseases." (PMID 37446225, 2023). "In recent years, thyrotropin-releasing hormone (TRH) and its analogs, including taltirelin (TAL), have demonstrated a range of effects on the central nervous system that represent potential therapeutic agents for the treatment of various neurological disorders, including neurodegenerative diseases." (PMID 35563779, 2022).
infection (5 papers, 2008 to 2026). The state of being infected such as from the introduction of a foreign agent such as serum, vaccine, antigenic substance or organism. "We found 56 ± 17% (n = 3 males, 72 h post infection) of PRV-GFP positive neurons expressed thyrotropin releasing hormone, TRH." (PMID 30917148, 2019). "In contrast the response against TrH antigens increased rapidly after the first infection and was maintained for a long period after the 4th infection." (PMID 19067839, 2008). "A significant increase in the level of anti-TrH IgG1 antibodies was detected only after the second infection, and there were further increases after the 3rd and 4th infections." (PMID 19067839, 2008). "Similar to the profile of IgG1, levels of TrH specific IgG2b antibodies increased only after the 2nd exposure and they remained elevated after the 3rd and the 4th infections with a slow progressive decline over the remaining time course." (PMID 19067839, 2008). "Exposure of mice to a single dose of infective T. regenti cercariae induced a significant increase in the level of anti-TrH IgM antibodies detected at 10 days after infection." (PMID 19067839, 2008). "Similar to the IgG1 response to TrH antigens, the IgG1 response to TrE/S antigens was delayed, with little increase detected after the 1st infection in contrast to the response after subsequent infections." (PMID 19067839, 2008).
neurologic disorders (5 papers, 2011 to 2022). "TRH analogs resistant to degradation by TRH-DE are promising for treating some neurological disorders." (PMID 32457627, 2020). "Initial results led to early attempts to use TRH and analogues with improved stability, agonist potency and/or brain accessibility for experimental treatment of psychiatric or neurological diseases." (PMID 32457627, 2020). "Several neurologic disorders improve with treatment with TRH and some of its stable analogs." (PMID 32457627, 2020). "Therefore, TRH and its analogs have great potential in treating many nervous system diseases." (PMID 30555300, 2018). "Gynecologists generally recognize TRH as the agent used in the TRH provocation test, but are not necessarily aware that this agent is also routinely used for the treatment of SCD, a neurological disorder." (PMID 22152284, 2011).
metabolic disorders (3 papers, 2020 to 2022). "Another gene within chromosome 3 CNV region is TRH (Thyrotropin releasing hormone); its function includes carbohydrate and amino acid metabolism, and it has been involved in endocrine system disorders, metabolic disease, and organismal injury." (PMID 33008348, 2020).
psychiatric disorder (3 papers, 2017 to 2019). A disorder characterized by behavioral and/or psychological abnormalities, often accompanied by physical symptoms. "The neuroanatomical location and neurochemical actions of TRH and its receptors suggest that it could be utilized as a therapeutic agent in neurological and psychiatric disorders." (PMID 28358038, 2017).
endocrine system disorder (2 papers, 2019 to 2020). A disease involving the endocrine system. "Concurrent testing for PPID and ID with a TRH stimulation test before an OST is an acceptable diagnostic tool for investigation of endocrinopathies in horses and allows accurate testing to be performed efficiently in 1 visit." (PMID 31432575, 2019).
hematological diseases (2 papers, 2022 to 2025). "Unlike AML patients, those with these hematological diseases presented relatively lower expression levels of TRH, suggesting that TRH was a characteristic biomarker for AML." (PMID 36291567, 2022).
cardiovascular disease (1 paper, 2024). "However, the triiodothyronine suppression test was contraindicated due to the patient’s cardiovascular disease, and the thyrotropin-releasing hormone stimulation test, measurement of glycoprotein hormone alpha-subunit, and genetic testing were unavailable." (PMID 38642582, 2024).
hematological cancers (1 paper, 2022). "With data from the MILE study, we analyzed and compared TRH expression in a variety of hematological cancers including ALL, CLL, CML, and MDS." (PMID 36291567, 2022).
kidney disorder (1 paper, 2021). A disease involving the kidney. "In addition, these kidney disorders can cause internal and external effects that can be reflected in alterations of the levels of thyrotropin-releasing hormone, pGlu-His-Pro-NH2 (TRH)." (PMID 34065436, 2021).
neuromuscular disease (1 paper, 2020). "For example, the administration of hypothalamic and pituitary hormones [growth hormone (GH) and thyrotropin releasing hormone (TRH)] or synthetic glucocorticoids (e.g., prednisolone), administered in case of several neuromuscular diseases can exert beneficial effects on muscle functions." (PMID 33281605, 2020).
TRH also shares sentences with these, for which no sentence is quoted: hypogonadism (4 papers); Insulin resistance (4); Adrenal insufficiency (3); Ataxia (3); dysplastic nevi (3); Hyperinsulinemia (3); malnutrition (3); mood disorder (3); hyperplasia (2); insomnia (2); metabolic acidosis (2); ovarian carcinoma (2); Sheehan Syndrome (2); thyroid abnormalities (2); thyroid cancer (2); type 2 diabetes mellitus (2); acute lymphoblastic leukemia (1); Addison disease (1); amyotrophic lateral sclerosis (1); Anterior hypopituitarism (1); benign neoplasm (1); Borderline personality disorder (1); brain diseases (1); brain injury (1); Cachexia (1); central nervous system disorder (1); cervical squamous cell carcinoma (1); chronic lymphocytic leukemia (1); cognitive decline (1); colon cancer (1).
A further 47 diseases each share a sentence with TRH in 1 paper.